CEND1 (cell cycle exit and neuronal differentiation 1)
Description:
Involved in neuronal differentiation.
Synonyms: BM88; FLJ90066
Tractability: Antibody: UniProt predicts a signal peptide or a membrane-spanning region. PROTAC: its protein half-life has been measured.
Gene: Protein-coding gene on chromosome 11 (787,115 to 790,113, reverse strand). Ensembl gene ENSG00000184524.
Subcellular location: Membrane
Subcellular location (Human Protein Atlas): Mitochondria
Gene Ontology:
Molecular function: protein binding
Biological process: cerebellar granular layer maturation; cerebellar Purkinje cell differentiation; radial glia guided migration of cerebellar granule cell; cerebellum development; neuron differentiation
Cellular component: mitochondrion; vesicle; membrane
Genetic constraint (gnomAD): Loss-of-function variants: 1 observed, 3.93 expected, observed/expected ratio (o/e) 0.25, 90% interval 0.089 to 1.19. That is too few expected variants to judge how well the gene tolerates losing a copy. Missense variants: 213 observed, 177.46 expected, observed/expected ratio (o/e) 1.2, 90% interval 1.07 to 1.35. Synonymous variants: 109 observed, 87.86 expected, observed/expected ratio (o/e) 1.24, 90% interval 1.06 to 1.46.
Homologues: Orthologues: chimpanzee CEND1 (99% identical), rat Cend1 (79% identical), dog CEND1 (79% identical), mouse Cend1 (79% identical), guinea pig CEND1 (77% identical), pig CEND1 (72% identical).
Diseases named in the same sentence as CEND1 in open-access papers:
CEND1 is named in the same sentence as 17 diseases in open-access papers, as found by Europe PMC text mining. Sharing a sentence is not in itself a finding about the gene and the disease. The quoted sentences say what the papers report.
neuroblastoma (3 papers, 2013 to 2024). Neuroblastoma (NB) is the most common solid, extracranial childhood tumor. "CEND1 was shown to suppress cell proliferation via modulating the cyclin D1 pathway, which is linked to its potential tumor suppressor functions, associated with proliferation inhibition of neuroblastoma cells." (PMID 32156068, 2020). "TSA upregulates the expression of BM88/cell cycle exit and neural differentiation protein 1 (CEND1), which is derived from neural crest stem cells, in neuroblastoma, and induces cancer cells to exit the cell cycle and differentiate." (PMID 37935080, 2024). "We next explored the functional significance of RanBPM binding to Cend1 in the mouse neuroblastoma Neuro 2a cell line." (PMID 24312406, 2013). "To elucidate a potential mechanism involving BM88/Cend1, RanBPM and Dyrk1B in cell cycle progression/exit, we transiently co-expressed these proteins in mouse neuroblastoma Neuro 2a cells." (PMID 24312406, 2013). "Further, by co-expression experiments in transiently transfected mouse neuroblastoma Neuro 2a cells, we found that the Cend1-dependent or Dyrk1B-dependent down-regulation of cyclin D1 is reversed following their interaction with RanBPM." (PMID 24312406, 2013). "In this study we identified a direct protein-protein interaction between Cend1 and the scaffolding protein RanBPM and demonstrated that this interaction reverses the anti-proliferative function of Cend1 in mouse neuroblastoma Neuro 2a cells." (PMID 24312406, 2013).
Cognitive impairment (2 papers, 2018 to 2024). Abnormal cognition is characterized by deficits in thinking, reasoning, or remembering. "In this work we identified increased anxiety-related behavior and cognitive impairment in adult Cend1-deficient mice that were accompanied by cellular alterations in functionally relevant brain areas." (PMID 30760981, 2018). "Overexpression of CEND1 in the hippocampus of 5 × FAD mice rescued cognitive deficits." (PMID 39872979, 2024).
Anxiety (1 paper, 2018). Intense feelings of nervousness, tension, or panic often arise in response to interpersonal stresses. "To further characterize the effects of Cend1 genetic ablation we determined herein a range of behaviors, including anxiety and exploratory behavior in the elevated plus maze (EPM), associative learning in fear conditioning, and spatial learning and memory in the Morris water maze (MWM)." (PMID 30760981, 2018). "To examine further the consequences of Cend1 genetic ablation, we determined herein a range of behaviors, including anxiety and exploratory behavior in the elevated plus maze (EPM), associative learning in fear conditioning, and spatial learning and memory in the Morris water maze (MWM)." (PMID 30760981, 2018).
Ataxia (1 paper, 2019). Ataxia refers to impaired coordination of voluntary muscle movement. "Interestingly, a study that produced an interaction network for 54 proteins involved in 23 human inherited ataxias characterized by loss of balance due to cerebellar Purkinje cell (PC) degeneration revealed that Cend1 is a direct protein partner of ataxin-1-interacting protein (A1Up)." (PMID 31191667, 2019). "This interactome map provides a tool for better understanding of pathogenic mechanisms common for this class of neurodegenerative disorders and for identifying candidate genes for inherited ataxias, providing an additional link for the role of Cend1 in cerebellar development and function." (PMID 31191667, 2019).
delirium (1 paper, 2026). A disorder characterized by confusion; inattentiveness; disorientation; illusions; hallucinations; agitation; and in some instances autonomic nervous system overactivity. "CEND1 role in delirium has also not been investigated so far." (PMID 41286463, 2026).
dementia (1 paper, 2013). Loss of intellectual abilities interfering with an individual's social and occupational functions. "Our study also indicates a crucial role of AHNAK in processes of aging-related dementia, and we hypothesize that the Cb exploits proteins such as CEND1 or GSN to fight against neurodegeneration." (PMID 24008896, 2013).
invasive breast carcinoma (1 paper, 2020). A carcinoma that infiltrates the breast parenchyma. "CEND1 was found to be epigenetically suppressed by methylation in invasive breast carcinoma, also suggestive for a potential tumor suppressor role in this cancer type." (PMID 32156068, 2020).
liver fibrosis (1 paper, 2025). "As for scarring, we identified the candidates Ppt1 and Cend1 that have demonstrated associations with kidney and liver fibrosis scarring, respectively." (PMID 41462614, 2025).
Zika virus infection (1 paper, 2019). "The NS4B-Cend1 interaction was validated upon ZIKV infection of SK-N-BE2 cells transduced with a lentivirus expressing Cend1, followed by reciprocal coimmunoprecipitation experiments." (PMID 31191667, 2019). "Interestingly, Cend1 knockdown resulted in inhibition of ZIKV replication, suggesting that Cend1 is a promising new therapeutic target in Zika virus infection." (PMID 31191667, 2019).
cancer (5 papers, 2019 to 2024). A tumor composed of atypical neoplastic, often pleomorphic cells that invade other tissues. "CEND-1 has been extensively studied as a potentially broadly applicable therapeutic enhancer of anti-cancer therapeutics." (PMID 36982773, 2023). "As the antiproliferative effect of Cend1 could be extended to nonneural cells, coupled to proapoptotic induction, we considered the possibility that Cend1 has a more generalized antitumor action that may become of use in cancer therapeutics." (PMID 31191667, 2019).
CEND1 also shares sentences with these, for which no sentence is quoted: autism (1 paper); glioma (1); Joubert syndrome (1); neurodevelopmental disorder (1); ovarian carcinoma (1); schizophrenia (1); tumor (1).